NDUFB8 (NADH:ubiquinone oxidoreductase subunit B8)
Description:
Accessory subunit of the mitochondrial membrane respiratory chain NADH dehydrogenase (Complex I), that is believed not to be involved in catalysis. Complex I functions in the transfer of electrons from NADH to the respiratory chain. The immediate electron acceptor for the enzyme is believed to be ubiquinone.
Synonyms: CI-ASHI; ASHI; MC1DN32
Tractability: Small molecule: an approved drug acts on it; a structure with a bound ligand is known. Antibody: UniProt predicts a signal peptide or a membrane-spanning region. PROTAC: ubiquitination databases record sites on it; its protein half-life has been measured.
Target class: Enzyme; Oxidoreductase
Gene: Protein-coding gene on chromosome 10 (100,523,668 to 100,530,000, reverse strand). Ensembl gene ENSG00000166136.
Subcellular location: Mitochondrion inner membrane
Subcellular location (Human Protein Atlas): Mitochondria
Pathways (Reactome):
Metabolism: Complex I biogenesis; Respiratory electron transport
Protein localization: Mitochondrial protein import
Gene Ontology:
Molecular function: NADH dehydrogenase (ubiquinone) activity
Biological process: aerobic respiration; mitochondrial electron transport, NADH to ubiquinone; proton motive force-driven mitochondrial ATP synthesis; proton transmembrane transport
Cellular component: mitochondrial inner membrane; mitochondrion; respiratory chain complex I; mitochondrial matrix
Genetic constraint (gnomAD): Loss-of-function variants: 17 observed, 27.21 expected, observed/expected ratio (o/e) 0.62, 90% interval 0.43 to 0.94. The upper end of that interval is the gene's LOEUF score, 0.94, which puts it in group 3 of 6, group 1 being the genes least tolerant of losing a copy. Missense variants: 238 observed, 266.02 expected, observed/expected ratio (o/e) 0.89, 90% interval 0.8 to 1. Synonymous variants: 89 observed, 98.46 expected, observed/expected ratio (o/e) 0.9, 90% interval 0.76 to 1.08.
Gene-disease validity (ClinGen):
ClinGen rates the evidence that NDUFB8 causes each of these diseases.
Leigh syndrome (autosomal recessive): Moderate. A progressive neurological disease defined by specific neuropathological features associating brainstem and basal ganglia lesions.
mitochondrial disease (autosomal recessive): Moderate.
Homologues: Orthologues: chimpanzee NDUFB8 (99% identical), macaque NDUFB8 (93% identical), pig NDUFB8 (85% identical), dog NDUFB8 (84% identical), rat Ndufb8 (83% identical), guinea pig NDUFB8 (81% identical), mouse Ndufb8 (81% identical), rabbit NDUFB8 (70% identical), zebrafish ndufb8 (66% identical), Drosophila melanogaster ND-ASHI (34% identical), Caenorhabditis elegans ndub-8 (29% identical).
Diseases named in the same sentence as NDUFB8 in open-access papers:
NDUFB8 is named in the same sentence as 43 diseases in open-access papers, as found by Europe PMC text mining. Sharing a sentence is not in itself a finding about the gene and the disease. The quoted sentences say what the papers report.
breast cancer (5 papers, 2021 to 2025). A primary or metastatic malignant neoplasm involving the breast. "Others, including Cox8a, Ndufb8, and Atad1, which are the genes involved in oxidative phosphorylation pathway, also exhibited an opposite regulation by Srsf3 KO in our Erbb2 breast cancer and DEN-induced liver cancer." (PMID 40568073, 2025). "We observed significant overexpression of NDUFB8 mRNA (p = 6.81E‐07) in breast cancer patients (n = 1097) compared to their normal counterparts (n = 114)." (PMID 37810173, 2023). "Notably, NDUFB8 mRNA expression was also found to be higher (p = 6.53E‐07) in the African (n = 179) compared to the Caucasian (n = 748) breast cancer patients." (PMID 37810173, 2023). "UQCRFS1, COX5B, and NDUFB8 expression was blunted by both SIRT6 silencing in MDA-MB-231 cells and by the Sirt6 heterozygous deletion in mouse mammary tumors." (PMID 33482921, 2021).
Parkinson disease (5 papers, 2016 to 2026). A progressive degenerative disorder of the central nervous system characterized by loss of dopamine producing neurons in the substantia nigra and the presence of Lewy bodies in the substantia nigra and locus coeruleus. "The Parkinson’s disease and Alzheimer’s disease pathways in the SncaG51D/G51D cortex were significant due to down-regulation of proteins involved in oxidative phosphorylation (NDUFAB1, COX5A, NDUFB8), and in the case of PD dopamine transport (SLC18A2)." (PMID 40574971, 2025).
Alpers syndrome (3 papers, 2022 to 2025). A cerebral degeneration that results in progressive degeneration of grey matter in the cerebrum and has_symptom convulsions. "Quantification of mean optical intensities revealed a high proportion of parvalbumin+ interneurons from all patients with Alpers' syndrome had combined severe NDUFB8 and COXI deficiencies." (PMID 35790454, 2022). "Interestingly, parvalbumin+ interneurons from patients with Alpers' syndrome showed a trend towards greater loss of COXI protein expression relative to NDUFB8." (PMID 35790454, 2022). "In Alpers’ syndrome, both NDUFB8 and COXI were significantly decreased in the granule cell layer relative to controls (P < 0.05), whereas in the late-POLG and mtDNA group, only COXI protein expression was significantly decreased." (PMID 40445405, 2025). "Quantification of the intensity of NDUFB8 and COXI proteins, normalised to porin, within Purkinje neurons revealed OXPHOS protein deficiencies involving both complexes in the Alpers’ syndrome patient group relative to matched controls (P < 0.05)." (PMID 40445405, 2025). "Analyses between the three disease groups revealed a significantly increased NDUFB8 and COXI deficiencies in Alpers’ syndrome in comparison to the mtDNA and late-POLG disease groups (P < 0.01)." (PMID 40445405, 2025). "Calretinin+ interneurons from Alpers' syndrome patient tissues displayed surprisingly low levels of NDUFB8 immunoreactivity and to a lesser extent decreased immunoreactivity of COXI within mitochondria compared with control interneurons." (PMID 35790454, 2022). "The levels of NDUFB8 and COXI deficiencies within calretinin+ interneurons were significantly less severe when compared with parvalbumin+ interneurons in the occipital and temporal cortices of almost all patients with Alpers' syndrome (Mann–Whitney, P < 0.05)." (PMID 35790454, 2022). "The immunoreactivity of NDUFB8 and COXI was variably decreased across Alpers’ syndrome patient tissues, despite visible levels of porin." (PMID 37259148, 2023). "A proportion of interneurons from SUDEP patients also harboured variably reduced levels of NDUFB8 and COXI protein levels, albeit less severe than the patients with Alpers' syndrome." (PMID 35790454, 2022).
colorectal cancer (3 papers, 2023 to 2024). A primary or metastatic malignant neoplasm that affects the colon or rectum. "Furthermore, NDUFB8, UQCRC2, COX4I1, and ATP5A low levels were associated with lower relapse-free survival in colorectal cancer patients." (PMID 39595536, 2024).
glioblastoma (3 papers, 2020 to 2024). The most malignant astrocytic tumor (WHO grade IV). "NDUFB8 was hypermethylated gene in glioblastoma which could be used as novel biomarkers for the prognosis." (PMID 38698303, 2024).
coronary artery disease (2 papers, 2024). "Other downregulated genes, such as NDUFA1 and NDUFB8, are related to coronary artery disease." (PMID 38396938, 2024). "NDUFB8 and NDUFA1 are known from patients with coronary artery disease (CAD)." (PMID 38396938, 2024).
COVID-19 (2 papers, 2023 to 2025). A disease caused by infection with severe acute respiratory syndrome coronavirus 2. "This study demonstrates that there is a persistent increased activation of nuclear-encoded OXPHOS genes namelyCOX7C, COX7A2, ATP5PO, ATP5F1C and NDUFB8 in blood tissue immediately following COVID-19 recovery, and then a time-dependent tapering off of these genes." (PMID 41141600, 2025). "However, under reduced oxygen saturation in the lung of COVID-19 patients, downregulation of genes encoding lipid uptake, FAO, and NADH oxidation (NDUFB8, NDUFA11, NDUFA13) was found in severe COVID(+) NKTs suggesting mitochondrial dysfunction in NKTs during SARS-CoV-2 infection." (PMID 37029220, 2023).
gastric adenocarcinoma (2 papers, 2021 to 2024). "NDUFB8 is a subunit of mitochondrial complex I, and the inhibition of NDUFB8 can mediate excessive ROS production and ATP depletion, which may induce apoptosis in gastric adenocarcinoma cells." (PMID 38843392, 2024). "GTT decreases the levels of the NDUFB8 subunit of complex I and SDHB subunit of complex II of the mitochondrial electron transfer chain, inhibits oxidative phosphorylation, increases generation of reactive oxygen species, and induces apoptosis in gastric adenocarcinoma cells." (PMID 34884479, 2021).
lung adenocarcinoma (2 papers, 2016 to 2019). A carcinoma that arises from the lung and is characterized by the presence of malignant glandular epithelial cells. "To determine whether DGUOK may indeed contribute to the biogenesis of mitochondrial respiratory complex I in cancer patients, we used IHC to determine the expression of NDUFB8 in our lung adenocarcinoma tissue microarray." (PMID 31633874, 2019). "The expression of NDUFB8 co‐localized with DGUOK in lung adenocarcinoma patient specimens." (PMID 31633874, 2019). "Spearman correlation analysis revealed robust correlation between NDUFB8 expression and DGUOK expression in the cohort of lung adenocarcinoma patients (r = 0.728, n = 113, P < 0.0001)." (PMID 31633874, 2019).
lung carcinoma (2 papers, 2016 to 2019). "We chose NDUFB8 because this is one of the most dramatically down‐regulated complex I proteins in DGUOK KO lung cancer cells, and also because we were able to obtain an anti‐NDUFB8 antibody suitable for IHC staining." (PMID 31633874, 2019).
melanoma (2 papers, 2012 to 2019). A malignant, usually aggressive tumor composed of atypical, neoplastic melanocytes. "c Expression levels of complex I subunit NDUFB8 in BRAF mutated melanoma (BRAFV600E; n = 24) and BRAF wild type melanoma (no BRAFV600E; n = 23)." (PMID 30971321, 2019). "b Immunohistochemistry of NDUFB8 in a human melanoma brain metastasis." (PMID 30971321, 2019). "Similar dose-dependent downregulation of NDUFB8, SDHB/Ip, and UQCR2 was also observed in the case of WM983-B melanoma cells (data not shown)." (PMID 22912665, 2012).
non-alcoholic fatty liver disease (2 papers, 2023 to 2024). "Six of the key metagenes—INSR, MAP3K5, NDUFB8, NDUFS1, SDHB, and UQCRC2—are involved in nonalcoholic fatty liver disease (hsa04932), which is caused by a defect in insulin suppression of free fatty acid (FAA) disposal due to the induction of insulin resistance." (PMID 36979367, 2023).
Sepsis (2 papers, 2018 to 2023). Sepsis is defined as life-threatening organ dysfunction caused by a dysregulated host response to infection. "The MtDNA copy number and mRNA expression of PGC-1α and NDUFB8 from the renal cortex were investigated and showed significant decreases following sepsis-induced AKI in the present study." (PMID 29682165, 2018). "Similarly, mRNA expression of PGC-1α (COX3: r = 0.543, P = 0.0109; ND1: r = 0.5992, P = 0.0041), and NDUFB8 (COX3: r = 0.549, P = 0.0100; ND1: r = 0.517, P = 0.0165) was reduced after sepsis-induced AKI, and their expression was also inversely associated with UmtDNA levels." (PMID 29682165, 2018).
acute kidney injury (1 paper, 2017). Sudden and sustained deterioration of the kidney function characterized by decreased glomerular filtration rate, increased serum creatinine or oliguria. "After ICH, although total SIRT1 expression increased, mitochondrial proteins, such as ATPβ, NDUFB8, and COX I, were reduced in the ICH group compared with shams, and this was also reported in acute kidney injury." (PMID 29375306, 2017).
androgen excess (1 paper, 2023). "The expression of NDUFB8 was reduced in an experimental model of androgen excess in rats, and these changes were also confirmed in a previous study on maternal nutrient restriction in baboon-cultured skin fibroblast." (PMID 37351104, 2023).
Barth syndrome (1 paper, 2025). Barth syndrome (BTHS) is an inborn error of phospholipid metabolism characterized by dilated cardiomyopathy (DCM), skeletal myopathy, neutropenia, growth delay and organic aciduria. "In the heart, the level of complex I protein NDUFB8 was significantly lower in TazmKO mice than in control mice, consistent with prior studies of hearts from Taz knockdown mice and patients with Barth syndrome." (PMID 40326536, 2025).
glioma (1 paper, 2021). A benign or malignant brain and spinal cord tumor that arises from glial cells (astrocytes, oligodendrocytes, ependymal cells). "In addition, we found that four of the candidate tumor gene biomarkers (NDUFS5, NDUFA1, NDUFA13, and NDUFB8) belong to the NADH ubiquinone oxidoreductase subunit gene family, so we inferred that this gene family may be strongly related to glioma." (PMID 34863158, 2021).
liver fibrosis (1 paper, 2024). "ART also reduced liver fibrosis caused by schistosomiasis through the downregulation of NDUFB8, a subunit of mitochondrial complex I, and UQCRC2, a subunit of mitochondrial complex III in hepatic stellate cells." (PMID 39476067, 2024).
multiple myeloma (1 paper, 2022). "Additionally, relapsed/refractory myeloma patients expressed significantly higher expression of NDUFB8, NDUFA6, COX6C, and USMG5 than newly diagnosed patients." (PMID 36551283, 2022). "Our results indicate that NDUFB8, NDUFA6, COX6C, COX5B, and USMG5 might influence the immune microenvironment of multiple myeloma patients, as well as the response to treatment and prognosis of patients with this disease." (PMID 36551283, 2022).
neuroblastoma (1 paper, 2023). Neuroblastoma (NB) is the most common solid, extracranial childhood tumor. "In our studies, KU-32 enhanced the Vmax of Complex I in mitochondria of neuroblastoma cells without affecting substantially the levels of a key organizing subunit of the complex, NDUFB8." (PMID 38035268, 2023).
ovarian carcinoma (1 paper, 2020). A malignant neoplasm originating from the surface ovarian epithelium. "Considering the age of the patient at the initial pathologic diagnosis, 18 competing triplets are found to be associated with the overall survival time of patients in ovarian cancer, including miR-224-5p/AL354892.2/ZBTB12, miR-3653-3p/FGD5-AS1/NR1D2, miR-224-5p/AC112491.1/NDUFB8, and so on." (PMID 33519912, 2020).
prostate carcinoma (1 paper, 2023). A carcinoma that arises from epithelial cells of the prostate gland. "Importantly, in POLRMT-silenced prostate cancer xenograft tissues, NDUFB8, UQCRC2, and COXI downregulation as well as oxidative stress, lipid peroxidation, and ATP reduction were detected as well." (PMID 37816734, 2023). "mRNA expression of key mitochondrial genes, including NDUFB8, UQCRC2, and COXI, was decreased with POLRMT silencing or inhibition, but increased with POLRMT overexpression in prostate cancer cells." (PMID 37816734, 2023).
tuberculous pleurisy (1 paper, 2021). "A total of eight possible biomarkers of tuberculous pleurisy were screened (RPL17, UBA7, NDUFB8, UQCRFS1, JUNB, PSMC4, PHPT1, and MAPK11)." (PMID 34925441, 2021).
tumor (7 papers, 2019 to 2026). "In vivo results reveal that NDUFB8 KD had a significant effect on tumor regression in 2 independent clones compared with controls." (PMID 39253977, 2024). "We then generated orthotopic xenograft using 2 independent clones of NDUFB8 KD in AA BLCA cell lines to measure the tumor growth." (PMID 39253977, 2024). "Consistent with TH287-induced mitochondrial accumulation in cultured HT1080 cells, the levels of mitochondrial components NDUFB8 and Cytochrome C, as examined by immunohistochemistry, were also increased in tumor grafts treated with TH287." (PMID 34773075, 2022). "Moreover, preclinical studies demonstrate the therapeutic potential of targeting complex I, as evidenced by decreased tumor growth in NDUFB8-depleted AA BLCA tumors." (PMID 39253977, 2024). "In addition, we found that four (NDUFS5, NDUFA1, NDUFA13, and NDUFB8) of the candidate tumor gene biomarkers belong to the NADH ubiquinone oxidoreductase subunit gene family." (PMID 34863158, 2021). "Increased NDUFB8 expression and complex I activity in AA BLCA tumors with enhanced glutamine uptake and elevated glutaminolysis induce tumor progression." (PMID 39253977, 2024). "Depletion of NDUFB8 (a complex I accessory subunit) reduced the OXPHOS-dependent ATP pool and abrogated the tumor growth in AA BLCA tumors, highlighting complex I role in linking race-specific mitochondrial activity and tumor progression in AA patients with BLCA." (PMID 39253977, 2024).
cancer (5 papers, 2019 to 2023). A tumor composed of atypical neoplastic, often pleomorphic cells that invade other tissues. "To evaluate CI activity and the potential clinical relevance of our findings, we performed immunohistochemical staining of NDUFB8 (accessory subunit of CI) in 197 human brain metastases from various cancers." (PMID 30971321, 2019). "EPHX2, ACSF2, CYP27A1, ACSS1, and ALDH1L1 showed hypermethylation in several types of human cancer; on the contrary, AKR1B10, POLG2, NDUFB8, ACACB, and MRPS22 consistently showed hypomethylation in several types of human cancer." (PMID 37223030, 2023).
infection (3 papers, 2007 to 2025). The state of being infected such as from the introduction of a foreign agent such as serum, vaccine, antigenic substance or organism. "In contrast, these genes were downregulated in C57BL/6 mice on day 2 post-infection and in CBA/J mice on day 7 post-infection, while only Ndufb8 was downregulated in CBA/J mice on day 2 post-infection." (PMID 18062806, 2007). "The expression of Uqcrq, Cox4i1, Ndufb8, Atp6v1g2 and Atp5b involved in oxidative phosphorylation was upregulated in CM-R mice on day 2 post-infection, suggesting that cerebral oxidative metabolism may be stimulated by PbA infection in CM-R mice." (PMID 18062806, 2007).
neurodegenerative disease (1 paper, 2023). A disorder of the central nervous system characterized by gradual and progressive loss of neural tissue and neurologic function. "Ultimately, the temporal dynamics of the expression profiles of genes associated with neurodegenerative diseases, such as Ndufa2, Ndufb6, Snca, Ndufb8 and Cox8a, were characterized by trending." (PMID 37834317, 2023).
NDUFB8 also shares sentences with these, for which no sentence is quoted: Alzheimer disease (3 papers); Huntington disease (2); bacterial sepsis (1); cervical cancer (1); dementia (1); gastric cancer (1); Impaired glucose tolerance (1); Insulin resistance (1); liver cancer (1); Malignant hyperthermia (1); nasopharyngeal carcinoma (1); pancreatic cancer (1); renal cell cancer (1); schistosomiasis (1); virus infection (1); Zinc deficiency (1).